CISTR (chondrogenesis-associated transcript)
Synonyms: CISTR-ACT; CISTRACT; re52431
Gene: Long non-coding RNA gene on chromosome 12 (53,739,758 to 53,757,243, reverse strand). Ensembl gene ENSG00000260492.
Diseases named in the same sentence as CISTR in open-access papers:
CISTR is named in the same sentence as 2 diseases in open-access papers, as found by Europe PMC text mining. Sharing a sentence is not in itself a finding about the gene and the disease. The quoted sentences say what the papers report.
liver fibrosis (1 paper, 2022). "The CISTR, IFT140, and RGS14 genes are likely novel candidate blood methylation biomarkers for the diagnosis of liver fibrosis in NAFLD." (PMID 35433752, 2022). "The CISTR, IFT140, and RGS14 genes are potential novel candidate BDM biomarkers for liver fibrosis and these pilot data suggest further work on BDM biomarkers is warranted." (PMID 35433752, 2022). "The roles of the CISTR, IFT140, and RGS14 genes in the onset of liver fibrosis in NAFLD patients and their roles in the blood and the relationship with liver fibrosis remain unclear." (PMID 35433752, 2022). "Genes such as CISTR, IFT140, and RGS14 that contain DMPs in the blood DNA of NAFLD patients may provide clues to investigate the role of DNA methylation in the progression of liver fibrosis." (PMID 35433752, 2022). "Therefore, the CISTR, IFT140, and RGS14 genes may be potential novel candidate blood methylation biomarkers for the diagnosis of liver fibrosis in NAFLD." (PMID 35433752, 2022).
cancer (1 paper, 2022). A tumor composed of atypical neoplastic, often pleomorphic cells that invade other tissues. "Interchromosomal interactions have been demonstrated between SOX9 and the lncRNA CISTR-ACT gene or the ATF4 and FIRRE genes to serve biological processes including mammalian development and differentiation, as well as cancer stemness." (PMID 34707247, 2022).